MORF4L2 (mortality factor 4 like 2)
Description:
Component of the NuA4 histone acetyltransferase complex which is involved in transcriptional activation of select genes principally by acetylation of nucleosomal histone H4 and H2A. This modification may both alter nucleosome - DNA interactions and promote interaction of the modified histones with other proteins which positively regulate transcription. This complex may be required for the activation of transcriptional programs associated with oncogene and proto-oncogene mediated growth induction, tumor suppressor mediated growth arrest and replicative senescence, apoptosis, and DNA repair. The NuA4 complex ATPase and helicase activities seem to be, at least in part, contributed by the association of RUVBL1 and RUVBL2 with EP400. NuA4 may also play a direct role in DNA repair when directly recruited to sites of DNA damage. Also a component of the MSIN3A complex which acts to repress transcription by deacetylation of nucleosomal histones.
Synonyms: KIAA0026; MRGX; MORFL2
Tractability: Antibody: its Gene Ontology location is reachable by antibodies, with high confidence. PROTAC: ubiquitination databases record sites on it; its protein half-life has been measured.
Gene: Protein-coding gene on chromosome X (103,675,360 to 103,688,158, reverse strand). Ensembl gene ENSG00000123562.
Subcellular location: Nucleus
Subcellular location (Human Protein Atlas): Nucleoplasm
Pathways (Reactome):
Chromatin organization: HATs acetylate histones
Gene Ontology:
Molecular function: protein binding
Biological process: positive regulation of double-strand break repair via homologous recombination; regulation of cell cycle; positive regulation of DNA-templated transcription; regulation of apoptotic process; regulation of double-strand break repair; regulation of transcription by RNA polymerase II; chromatin organization; regulation of DNA-templated transcription
Cellular component: NuA4 histone acetyltransferase complex; nucleolus; nucleoplasm; nucleosome; nucleus
Homologues: Orthologues: macaque MORF4L2 (99% identical), dog MORF4L2 (99% identical), pig MORF4L2 (98% identical), rat Morf4l2 (95% identical), mouse Morf4l2 (95% identical), rabbit MORF4L2 (92% identical), rat RGD1564748 (57% identical), Drosophila melanogaster MRG15 (44% identical). Paralogues in human: MORF4L1 (75% identical), MSL3 (28% identical), MSL3B (22% identical).
Diseases named in the same sentence as MORF4L2 in open-access papers:
MORF4L2 is named in the same sentence as 12 diseases in open-access papers, as found by Europe PMC text mining. Sharing a sentence is not in itself a finding about the gene and the disease. The quoted sentences say what the papers report.
breast carcinoma (2 papers, 2015 to 2024). "For example, MORF4L2, PKG1, VPS28, and KLHDC7B predict the survival time of patients, indicating that cancer domains also facilitate the identification of bio-markers for breast cancer." (PMID 38783355, 2024).
Cognitive impairment (1 paper, 2016). Abnormal cognition is characterized by deficits in thinking, reasoning, or remembering. "Moreover, Mrgx, the mouse orthologue of MORF4L2 (aka MRGX, MIM 300409) has been shown to interact with HNRNPK, a gene known to be associated cognitive impairment." (PMID 27506666, 2016).
coronary heart disease (1 paper, 2022). "Significantly upregulated were gene regulators of VSMC differentiation, triggers of cell apoptosis, inflammation and coronary heart disease markers (Itih4, Tppp3, Slc25a39, CD44) in parallel to atheroprotective genes such as Morf4l2." (PMID 35163719, 2022).
head and neck squamous cell carcinoma (1 paper, 2025). A squamous cell carcinoma that arises from any of the following anatomic sites: lip and oral cavity, nasal cavity, paranasal sinuses, pharynx, larynx, and salivary glands. "Only one study on head and neck squamous cell carcinoma found that MORF4L2 was a prognostic biomarker for immunotherapy." (PMID 39780291, 2025).
tumor (8 papers, 2015 to 2025). "It was also found that miR-3156-5p directly targets MORF4L2, given that miR-3156-5p upregulation causes a decrease of MORF4L2 expression, which plays an important role in the activation of oncogene and proto-oncogene-mediated growth induction, as well as in tumor suppressor-mediated growth arrest." (PMID 36896239, 2023). "Two DRGs, GNPNAT1 and MORF4L2, exhibited strong correlations with survival prognosis and tumor-infiltrating immune cells (CD8+ T cells, macrophages, etc.)in the analysis above." (PMID 37033959, 2023). "Five of these signaling proteins (CDKN1B, CDKN1C, PTN, GJA1, and MORF4L2) can act as tumor suppressors." (PMID 32168333, 2020). "Therefore, a macrophage-tumor cell co-culture model was constructed, and it was verified that Morf4l2 induced the recruitment of mouse macrophage (RAW246.7) cells." (PMID 39780291, 2025). "Furthermore, MORF4L2 was subsequently verified to be highly expressed in tumor cells, especially in metastatic tumor cells." (PMID 39780291, 2025). "Thus, longitudinal analysis of miR-3156-5p and MORF4L2 within an individual MEN1 patient could provide important information on when tumour development has occurred and aid in determining the appropriate timing to initiate more invasive screening methods." (PMID 35900839, 2022). "In the Morf4l2 knockdown group, anti-PD1, BLZ945, and BLZ945 plus anti-PD1 partially suppressed tumor growth, whereas in the control group, BLZ945 plus anti-PD1 evidently suppressed tumor growth." (PMID 39780291, 2025). "Results showed that the expression level of genes including MORF4L2, CTSL1, WIPF1, CXCL13, C5orf15, LIPA, and ISG20 significantly elevated in tumor tissues." (PMID 36639648, 2023). "Based on TCGA and FUSCC databases, MORF4L2 mRNA expression was dramatically elevated in tumor tissues compared with non-carcinoma samples." (PMID 39780291, 2025). "However, SAHA significantly enhanced the tumor initiating capacity and the expression of malignant genes such as KCNMA1, MORF4L2 and ASPM in the remaining living ALDHbr cells." (PMID 25796627, 2015). "Therefore, our data do not take into account tumour size, ongoing treatments or miR-3156-5p and MORF4L2 expression levels with the tumours." (PMID 35900839, 2022).
MORF4L2 also shares sentences with these, for which no sentence is quoted: cancer (4 papers); adenocarcinoma (1); atherosclerosis (1); glioblastoma (1); lung carcinoma (1); Pelizaeus-Merzbacher disease (1); triple-negative breast carcinoma (1).